IL17A (interleukin 17A)
Diseases named in the same sentence as IL17A in open-access papers (continued):
Sharing a sentence is not in itself a finding about the gene and the disease.
psoriasis (continued). "Here we summarize the recent literature concerning the potential mechanisms of IL-17A that is involved in the comorbidity of psoriasis and atherosclerosis, thus providing a theoretical basis for IL-17A inhibitors treating patients with psoriasis and comorbid atherosclerotic disorders." (PMID 35514987, 2022). "In this psoriasis-like model, Tγδ17 cells expand in the LN and then migrate to the inflamed skin, where they contribute to the development of the skin lesions through the secretion of IL-17A." (PMID 35432331, 2022). "Low levels of 5-HT increase the production of some inflammatory mediators, such as TNF-α and IL-1β, which induces the activation and deterioration of keratinocytes via NF-kB, which is activated by IL-17A in the prefrontal cortex and in the hippocampus, thus worsening the symptoms of psoriasis." (PMID 35335319, 2022). "The efficacy of anti-IL-17R and anti-IL-17 agents has been shown in Phase II and III trials, indicating that IL-17A might have impact on the pathogenesis of psoriasis." (PMID 36300118, 2022). "In the present study, we found that 100 μM of forsythoside A could reduce the IL-17A concentration in vitro, suggesting the possibility of forsythoside A as a new promising small-molecule drug for psoriasis that targets IL-17A." (PMID 35055377, 2022). "While direct quantification of free IL-17A levels at the site of action is technically challenging, integrated mPBPK-MBMA approaches offer quantitative predictions of free IL-17A levels at the site of action to facilitate future drug development via IL-17A suppression in psoriasis." (PMID 35548359, 2022). "In addition, SPRR2C, a potential regulator that modulates IL-22 stimulation, was upregulated in both atopic dermatitis and psoriasis lesional skin and was also downstream of the IL-17A and IL-17 + TNF signaling in keratinocytes." (PMID 35559048, 2022). "In addition, recent studies revealed that IFN-γ and IL-17A, secreted from Th1 and Th17 cells, respectively, are crucial mediators to induce and accelerate the pathological progression of psoriasis and IBD." (PMID 36591260, 2022). "Treatment with anti-IL-17A antibody efficiently eradicated cutaneous lesions and decreased peripheral oxidative stress in two (CD11c-IL-17Aind/ind mice and mice with imiquimod induced psoriasis) assessed the models of psoriasis." (PMID 35313642, 2022). "IL-17C shares several commonalities with IL-17A, in terms of immune and pro-inflammatory effects, and together with IL-17A forms a hypothetical “feed-forward” model contributing to keratinocyte hyperplasia and systemic inflammation in psoriasis." (PMID 35008981, 2022). "Th17 cells could infiltrate the psoriatic skin lesions, and inhibition of IL-17A had an effective treatment for psoriasis." (PMID 35459141, 2022). "Indeed, topical application of maresin-1 showed anti-inflammatory effects in an imiquimod-induced psoriasis mouse model by inhibiting the production of IL-17A by γδTCR mid+ and CD4+ cells in the skin through repression in IL-23 receptor expression." (PMID 35886846, 2022). "We observe that single transcripts of disease-promoting cytokines, namely IFNG for LP, IL13 for AD, and, IL17A for psoriasis initiate localized amplification cascades of specific inflammatory responder genes that collectively represent hallmarks of the respective disease pathogenesis." (PMID 36513651, 2022). "Rather promisingly, new data on the roles of IL-17A and Claudin-1 and on the regulation of Claudin-1 by IL-17A in psoriasis may indicate new therapeutic approaches." (PMID 35340911, 2022). "Besides, much higher levels of IL-17F than IL-17A protein have been detected in the serum of patients with psoriasis." (PMID 36614836, 2022).
psoriasis (continued). "Statistical analyses were performed to determine differences in serum levels of IL-17A and Claudin-1, their bivariable correlation with psoriasis severity, as Psoriasis Area Severity Index (PASI), and their predictive abilities using receiver operating characteristic (ROC) curves." (PMID 35340911, 2022). "Also, this pathway activation and inhibition of autophagy have been reported to modulate cholesterol levels in IL-17A mediated inflammatory responses in psoriasis." (PMID 36741386, 2022). "However, recent scRNA-seq data showed the possibility that IL-17A producing T17 cells and IL-17F producing T17 cells are different T17 cell subsets in human psoriasis skin." (PMID 36110854, 2022). "Previously, it was hypothesized that the primary source of IL-17A in psoriasis was T helper 17 (Th17) cells." (PMID 35401573, 2022). "TNF-α /IL-17A/ IFN-γ are known to be psoriasis-inducing mediators in the immune system of skin." (PMID 36015080, 2022). "An IL-17A dominance has also been shown in human psoriasis cases." (PMID 35514987, 2022). "Furthermore, we found that MUP inhibited the process of IMQ-induced psoriasis-like dermatitis in vivo by inhibiting the activity of IL-17A signaling." (PMID 36419191, 2022). "IL-17A and IL-22 are produced by Th-17 cells and elevated levels of these cytokines are thought to be involved in the development and pathogenesis of autoimmune diseases, including psoriasis." (PMID 35337918, 2022). "Since the expression of immune regulatory genes is high in mild psoriasis, it was hypothesized that treatment response and disease remission in mild psoriasis after IL-17A inhibition might differ from those with severe psoriasis." (PMID 36110854, 2022). "For example, the action of IL17A has been shown to be central to the development of skin inflammation in psoriasis and, indeed, several biologics targeting the cytokine can greatly improve the symptoms of psoriasis in large percentages of patients." (PMID 36028520, 2022). "Therefore, IL17A-inhibitors are considered a safe choice to treat patients affected by psoriasis with LTBI." (PMID 35203438, 2022). "However, pathways involved in interleukin-17 (IL-17) signaling, including “Role of IL-17A in Psoriasis”, “IL-17A Signaling in Gastric Cells”, and “IL-17 Signaling” were predicted to be inhibited." (PMID 35783265, 2022). "In the present study, we report the first two psoriasis patients treated with bimekizumab after its European Medicines Agency approval who failed to treatment with anti-IL-17A therapy but responded to the blockade of IL-17A/IL-17F." (PMID 36614836, 2022). "Indeed, recent reports have shown that IL-17A plays a role in skin wound healing and gut epithelial repair while αIL-17A and αIFNγ mAbs have been developed to treat psoriasis and lymphohistiocytosis, respectively, in humans, with favorable outcomes." (PMID 35185884, 2022). "The combination of IL-17A and Claudin-1 exhibited equal performance in discriminating psoriasis from controls (AUC: 0.949, p < 0.0001), with the model comprising only IL-17A (AUC: 0.951, p < 0.0001), which performed better than the model including just Claudin-1 (AUC: 0.709, p = 0.0119)." (PMID 35340911, 2022). "Recently, bi-specific antibody directed against both IL-17A and IL-17F (bimekizumab) was tested in psoriasis and may be more effective than secukinumab, which only inhibits IL-17A." (PMID 35479069, 2022). "In addition, the inhibition of IL-17A attenuates the ROS level in the psoriasis-like mouse model blood sample." (PMID 36498953, 2022). "In this context, targeting the IL-17 cytokine family (IL-17A, IL-17F, and IL-17 receptor A) may be considered as a potential therapeutic strategy in the treatment of psoriasis and psoriatic arthritis." (PMID 36430483, 2022).
psoriasis (continued). "Among them, type 3 ILCs (ILC3s) play a central role in the etiology and disease severity of psoriasis, which was ascribed to the elevated number of IL-22- and IL-17 A/F-producing ILC3s induced by their expression of RORγt transcription factors in psoriatic skin and blood." (PMID 36242051, 2022). "Although traditionally, research has focused on the role of αβ T cells, it has become increasingly evident that γδ T cells, particularly those that are IL-17A-producing, contribute to inflammatory skin diseases, such as psoriasis and allergic contact dermatitis." (PMID 35888633, 2022). "The IL-17 cytokine family consists of six members (IL-17A, IL-17B, IL-17C, IL-17D, IL-17E and IL17F), with IL-17A and IL-17F being primarily associated with clinically relevant signaling in psoriasis, acting through the same receptor, but with varying potencies." (PMID 35883760, 2022). "The study showed that the impact of systemic IL-17A inhibition on psoriasis patients’ skin immunity was not confined to only blocking the major cytokine of pathogenic T-cells (IL-17A)." (PMID 36110854, 2022). "In addition, a mouse strain that expressed transgenic IL-17A in its skin developed severe psoriasis-like skin inflammation, suggesting that this cytokine plays an important role in psoriasis." (PMID 35884790, 2022). "Brodalumab is yet another monoclonal antibody with anti-IL-17A activity approved for the treatment of moderate-severe psoriasis in those who are adequate candidates for phototherapy or systemic therapy and have either lost response or failed to respond to systemic therapy." (PMID 35741329, 2022). "We therefore hypothesized that IL-17A might serve as an important messenger in mediating the crosstalk between keratinocytes and neutrophils in the context of psoriasis." (PMID 35401573, 2022). "Considering that blocking IL-17A is a fast and effective therapeutic strategy for psoriasis, it may be possible to exploit the self-assembled RSE model to identify key acting cytokines in disease pathogenesis." (PMID 35745784, 2022). "By contrast, pruritus in psoriasis patients is often mild or even absent, and the immune mechanism of psoriasis appears to be activated by Th17 cells and is associated with high levels of IL-17A and IL-17F." (PMID 36314037, 2022). "Treatment of IL-17A inhibitors leads to rapid and extensive clearance of neutrophils, which occurred parallel to the improvement of epidermal changes and clinical signs of psoriasis." (PMID 35401573, 2022). "IL-17A-neutralizing antibodies are well established as a treatment of psoriasis." (PMID 36139479, 2022). "The high affinity of brodalumab to human IL-17RA blocks the biological activities of the pro-inflammatory cytokines IL-17A, IL-17C, IL-17E, IL-17F, and IL17A/F heterodimer, resulting in inhibition of the inflammation and clinical symptoms associated with psoriasis." (PMID 36232430, 2022). "As seen in psoriasis, the synergy between IL-17A and TNFα is involved in the pathogenesis of RA." (PMID 36140808, 2022). "In line with the immunosuppressive therapy approach, further studies have shown that targeted therapy reduced cardiovascular mortality in rheumatoid arthritis (IL-6, TNF-α, and IL-17A cascades), lupus erythematosus (IL-17A signaling) (Crispín and Tsokos, 2010), and psoriasis (IL-17/IL-23)." (PMID 36267276, 2022). "In this study, we used HaCaT keratinocytes stimulated with M5, a cocktail of five inflammatory cytokines (TNF-α, oncostatin M, IL-1α, IL-17A, and IL-22), as an in vitro model of psoriasis with typical upregulation in the production of cytokines, chemokines, and antimicrobial peptides." (PMID 36555642, 2022). "It is noteworthy that the role of IL-17A in psoriasis, eukaryotic initiation factor 2 (eIF2) signaling, and the coronavirus pathogenesis pathway had the top three highest ratios (mapped DEGs divided by total molecules in a given pathway = 0.36, 0.30, and 0.25, respectively)." (PMID 35563374, 2022).
psoriasis (continued). "It has been proved that IL-23/IL17A axis plays a pivotal role in the pathogenesis of psoriasis." (PMID 35922852, 2022). "It was long thought that the primary source of IL-17A in psoriasis was Th17 cells." (PMID 35401573, 2022). "Biologics targeting IL-17A alone or in combination with IL-17F or the IL-17 receptor A (IL-17RA) are efficacious in the treatment of plaque psoriasis, highlighting the central role of the IL-17A pathway in psoriasis pathogenesis." (PMID 34616394, 2021). "Although IL-17A mAbs cannot be used to effectively treat cardiovascular events, further studies may provide novel therapies for psoriasis patients with CVDs or for cardiovascular patients." (PMID 33602246, 2021). "Interestingly, VEGF-A expression in skin biopsy specimens from psoriasis patients was reduced after IL-17A inhibition with secukinumab." (PMID 34201664, 2021). "Psoriasis is one of the most typical IL-17A-driven human diseases." (PMID 34267747, 2021). "Th17 cells produce IL-17A and IL-22, which are the main cytokines in the pathogenesis of psoriasis." (PMID 33483537, 2021). "IL-17A is by far the most studied IL-17 isoform in psoriasis CV comorbidities." (PMID 34201664, 2021). "Over the last two decades, significant advances in understanding the pathogenic mechanisms underpinning psoriasis, have led to the adoption of biological treatments (“biologics”) targeting the key cytokines TNF, IL-23 and IL-17A, which have transformed disease management." (PMID 34362923, 2021). "Notably, CA-induced IL-17F and IL-17A levels in CLA+T cells were significantly higher in cocultures from guttate psoriasis compared to those of plaque psoriasis." (PMID 33546306, 2021). "Besides, CXCL13, which achieved greater accuracy than IL-17A, was thought as a novel biomarker of psoriasis severity." (PMID 34777377, 2021). "We also examined γδ T cells, the predominant producers of IL-17A during psoriasis." (PMID 34215755, 2021). "This study deepened the research of IMQ-induced psoriasis model, fully illustrating the dose-dependent phenotype and strategy of avoiding adverse effect; meanwhile, it broadens the understanding of IL17A in psoriasis pathogenesis, as well as modulating IL17A pathway for treatment of psoriasis." (PMID 33509093, 2021). "Luteolin reduced IL-1β, IL-17A, IL-23, and IL-6 which could contribute to the anti-inflammatory effects of this flavonoid and the reduction of psoriasis damage in the mice model." (PMID 34943117, 2021). "Future efforts are anticipated to therapeutically explore the potential of our findings in diseases marked by increased IL-17A levels and platelet reactivity or angiogenic responses, such as rheumatoid arthritis, atherosclerosis, psoriasis, cancer and myocardial infarction." (PMID 34440624, 2021). "In addition, there is an imbalance between the differentiation and proliferation of keratinocytes in patients with psoriasis, and IL-17A can promote the proliferation of epidermal keratinocytes." (PMID 34134787, 2021). "Therefore, our in vitro psoriasis model using primary keratinocytes isolated from the skin of healthy donors treated with a combination of IL-17A, IL-22 and TNF-α provides an interesting substitute model that has already proven its capability." (PMID 34641358, 2021). "It has been stablished that the most important signalling in psoriasis is mediated by a receptor that could be activated by two different cytokines, IL-17A and IL-17F, IL-17A having a stronger effect." (PMID 34067151, 2021). "Therefore, when comparing patients with psoriasis (n = 15) and healthy controls (n = 20), we measured the amount of IL-17A in the supernatant of each culture and subsequently used it to normalize CYP1A1 activity." (PMID 33385398, 2021). "Extensive evidence indicates that IL-17A plays a key role in the pathogenesis of psoriasis." (PMID 34122457, 2021). "In addition, IL-1β, IL-23 and IL-17a are also very important cytokines involved in the pathogenesis of psoriasis." (PMID 34220863, 2021).
psoriasis (continued). "IL-17A monoclonal antibodies (mAbs) have shown clinical efficacy in psoriasis patients." (PMID 33602246, 2021). "First, although there have been many metabolomic analyses comparing healthy people and psoriasis patients, few studies have performed metabolic profiling of changes induced by IL-17A mAb treatment, eapecially alterations in lipid metabolism, in psoriasis patients." (PMID 33602246, 2021). "Although T cell and antigen-presenting cells have been known to be involved in the pathogenesis of psoriasis, neutrophils play a critical role by infiltrating the epidermis and secreting copious amounts of IL-17A, thus affecting keratinocytes and leading to skin proliferation." (PMID 34955833, 2021). "Especially IL-17A and TNF-α display an important inflammatory effect in the pathogenesis of psoriasis, whereas only IL-22, but not IL-17A and TNF-α, cause epidermal alterations typical for psoriasis such as acanthosis." (PMID 33801280, 2021). "IL-17A seems to fulfil a key role in the pathway of the pathogenesis of psoriasis, and biological therapies targeting IL-17A and/or IL-17RA yield remarkable effects for inflammatory skin dermatoses like psoriasis." (PMID 34945130, 2021). "Notably, blockade of IL-17RA using Brodalumab, a co-receptor for IL-17A, IL-17F and IL-25, has shown high efficacy in the treatment of psoriasis." (PMID 34122457, 2021). "IL-17A is a key cytokine that participates in the pathogenesis of psoriasis." (PMID 35186952, 2021). "Antibodies against IL‐17A or IL‐17 receptor are approved for the treatment of psoriasis and are currently being evaluated for treatment of inflammatory diseases and different cancers and should also be considered for cervical cancer therapy, potentially in combination with chemoradiotherapy." (PMID 34469022, 2021). "Therefore, we established psoriasis-like HPK by treating HPK with the cytokines IL-17A, TNF-α and IL-22." (PMID 33801280, 2021). "IL-17A is reported as necessary to produce IL-23-mediated psoriasis-like inflammation." (PMID 33483537, 2021). "Additionally, ethanol extract (SEL001), isolated from Lactobacillus sakei proBio-65, exhibited protective effects on imiquimod-treated psoriasis-like skin inflammation in a mouse model, with decreased gene expression levels of IL-19, IL-17A and IL-23." (PMID 34576860, 2021). "Since dysregulated lipid metabolism has been regarded as the critical factor in cardiovascular events, the recovery of lipid profiles in psoriasis patients indicates that IL-17A mAbs might have a protective effect against CVDs." (PMID 33602246, 2021). "Bimekizumab, targeting both IL-17A and IL-17F, is in phase 3 clinical trial for psoriasis." (PMID 34938746, 2021). "Furthermore, a group of IL-17A+/Foxp3+/CD4+ triple-positive cells were identified in the lesional skin of psoriasis patients." (PMID 34975883, 2021). "Moreover, miR-340 directly targets the pro-inflammatory cytokines IL-4 and IL-17A in psoriasis mice model, where Th17 cells and the consequent IL-17A production are implicated in the pathogenesis of this autoimmune disease as in others such as IBD." (PMID 34884564, 2021). "Cytokines or mediators that are upregulated in psoriasis, such as IL-23, IL-17A, IL-6, and IL-21, may induce the conversion of Tregs into Th17/Th1 cells." (PMID 34501328, 2021). "This study involved an exploration of the effects of FZHFZY on epidermal differentiation and its underlying mechanisms in interleukin (IL)-17A/IL-22/interferon (IFN)-γ/tumour necrosis factor (TNF)-α–stimulated HaCaT cells and in a mouse model of imiquimod (IMQ)-induced psoriasis." (PMID 34456715, 2021). "Disruption of the regulatory functions of Treg cells may lead to an increase the expression of IL-17A in psoriasis." (PMID 33356031, 2021). "Consequently, exposure of keratinocytes to the IFN-γ/IL-17A/IL-22 cytokine combination represents a reliable psoriasis-like in vitro model." (PMID 33986690, 2021).